CRMP1 (collapsin response mediator protein 1)
Diseases named in the same sentence as CRMP1 in open-access papers (continued):
Sharing a sentence is not in itself a finding about the gene and the disease.
breast carcinoma (3 papers, 2019 to 2025). "In addition, Cancer Genome Atlas (TCGA) data showed that RASGRF2, AKR1B1 and CRMP1 were low expressed in breast Cancer tissues, while RHOF was high expressed in breast Cancer tissues." (PMID 36454866, 2022). "Therefore, methylation of CRMP1 promoter may serve as a therapeutic target and prognostic biomarker for breast cancer with ALNM." (PMID 36454866, 2022). "AKR1B1, RASGRF2, CRMP1, BNIP3, GSTP1, HOXA5 and PAX6 genes were methylated in ER-positive and HER2-negative breast cancer with ALNM." (PMID 36454866, 2022). "But TCGA data showed that RASGRF2, AKR1B1 and CRMP1 were low expressed in breast Cancer tissues, while RHOF was high expressed in breast Cancer tissues." (PMID 36454866, 2022). "However, low expression of CRMP1 may lead to ALNM of breast cancer." (PMID 36454866, 2022). "Moreover, in addition to highly methylated AKR1B1, RASGRF2 and CRMP1 gene promoters, BNIP3, GSTP1, HOXA5 and PAX6 gene promoters were also methylated in ER-positive and HER2-negative breast cancer with ALNM." (PMID 36454866, 2022). "Therefore, our study identified RHOF, CRMP1, BNIP3 and HOXA5 as novel candidate methylation biomarkers, which can be used to predict ALNM in breast cancer or ER-positive and HER2-negative breast cancer." (PMID 36454866, 2022). "Furthermore, in addition to highly methylated AKR1B1, RASGRF2 and CRMP1 gene promoters, BNIP3, GSTP1, HOXA5 and PAX6 gene promoters were also methylated in ER-positive and HER2-negative breast cancer with ALNM." (PMID 36454866, 2022). "Moreover, it has been reported that miR‐200a is related to the occurrence and development of endometrial cancer, breast cancer, and esophageal cancer by targeting genes, such as PTEN, EPHA2, and CRMP‐1." (PMID 30784214, 2019). "Additionally, aberrant methylation patterns in the AKR1B1, RASGRF2, CRMP1, BNIP3, GSTP1, HOXA5, and PAX6 genes have been observed in estrogen receptor (ER)-positive and HER2-negative breast cancer with axillary lymph node metastasis (ALNM), suggesting their potential as therapeutic targets." (PMID 40517231, 2025). "Our study also found that the CRMP1 promoter is highly methylated in lymph node metastatic breast cancer tissues, which may result in lower CRMP1 expression in positive lymph node tissues than in negative lymph node tissues." (PMID 36454866, 2022). "Furthermore, in addition to highly methylated AKR1B1, RASGRF2 and CRMP1 gene promoters, BNIP3, GSTP1, HOXA5 and PAX6 gene promoters were also methylated in ER-positive and HER2-negative breast cancer with ALNM, which may serve as candidate methylation biomarkers." (PMID 36454866, 2022). "And compared with ER-positive and HER2-negative breast cancers without ALNM, the methylation levels of AKR1B1, RASGRF2, CRMP1, BNIP3, GSTP1, HOXA5, and PAX6 promoter were increased in ER-positive and HER2-negative breast cancers with ALNM." (PMID 36454866, 2022). "The results showed that compared with negative lymph node breast cancer tissues, RHOF promoter methylation levels were decreased in positive lymph node breast cancer tissues, while AKR1B1, RASGRF2, and CRMP1 gene promoter methylation levels were increased." (PMID 36454866, 2022). "Targeted bisulfite sequencing showed that the promoter methylation levels of AKR1B1, BNIP3, CRMP1, GSTP1, HOXA5, PAX6, and RASGRF2 were increased in ER-positive and HER2-negative breast cancers with ALNM, compared with ER-positive and HER2-negative breast cancers without ALNM." (PMID 36454866, 2022).
glioblastoma (3 papers, 2014 to 2022). The most malignant astrocytic tumor (WHO grade IV). "We demonstrate the potential use of NAP1L1, NUCL, CRMP1, ACTB, and VIM for differentiation between glioblastoma and lower grade gliomas, with DPYSL2 as a promising “glioma versus reference” biomarker." (PMID 28498803, 2017).
glioma (3 papers, 2015 to 2020). A benign or malignant brain and spinal cord tumor that arises from glial cells (astrocytes, oligodendrocytes, ependymal cells). "CRMP1 (collapsin response mediator protein 1) has been reported to be associated with medulloblastoma and gliomas." (PMID 32064261, 2020). "Bioinformatic analysis of genes of interest against TCGA RNA sequencing data proposed TRIM28, VIM, NAP1L1 and DPYSL2 as promising “glioma versus reference” biomarkers, and suggested CRMP1, NAP1L1, NUCL, ACTB and VIM for discrimination between GBM and LGG." (PMID 28498803, 2017). "Our results are in concordance with previous finding demonstrating involvement of CRMP1 in cancer invasion in lung, gliomas and prolactin pituitary tumors." (PMID 26009886, 2015).
lymph node metastasis (3 papers, 2014 to 2022). "However, our study found for the first time that methylation of RHOF, CRMP1, BNIP3 and HOXA5 promoters is associated with lymph node metastasis." (PMID 36454866, 2022). "The median value of CRMP1 mRNA expression was used to classify patients into high or low expression groups, whereby patients with low CRMP1 expression were found to exhibit a more advanced level of disease and lymph node metastasis." (PMID 24765134, 2014). "However, methylation of RHOF, CRMP1, BNIP3 and HOXA5 promoters has not been reported to be associated with lymph node metastasis, and our study is the first to find that methylation of these gene promoters is associated with lymph node metastasis." (PMID 36454866, 2022).
non-small cell lung carcinoma (3 papers, 2013 to 2016). A group of at least three distinct histological types of lung cancer, including non-small cell squamous cell carcinoma, adenocarcinoma, and large cell carcinoma. "The results indicted that the expression of CRMP1 mRNA in non-small cell lung cancer (NSCLC) was significantly lower than that in the adjacent normal tissues." (PMID 24765134, 2014).
bipolar disorder (2 papers, 2018 to 2024). A disorder of the brain that causes unusual shifts in mood, energy, activity levels and the ability to carry out day-to-day tasks. "In another study in patients with bipolar disorder, an association was found in mRNA levels of glycogen synthase kinase-3 (GSK3β) and collapsin response mediator protein 1 (CRMP1) with disease status and the severity of mood symptoms." (PMID 38654728, 2024).
depression (2 papers, 2018 to 2025). "Another gene linked to anxiety/depression whose expression was significantly altered in the prefrontal cortexes of DDW-exposed old mice was Crmp1." (PMID 41226662, 2025). "We have showed that decrements in CRMP1 expression were significantly related to lithium-associated changes in the severity of depression and mania, suggesting that CRMP1 pathway might be involved in mood-stabilizing effects of lithium." (PMID 29666369, 2018).
epilepsy (2 papers, 2017 to 2021). A brain disorder characterized by episodes of abnormally increased neuronal discharge resulting in transient episodes of sensory or motor neurological dysfunction, or psychic dysfunction. "The specific role of CRMP1 in CCD with epilepsy needs further evaluation." (PMID 28222113, 2017). "It is possible that CRMP1 plays different roles in CCD with epilepsy and TLE." (PMID 28222113, 2017).
Huntington disease (2 papers, 2022). Huntington disease (HD) is a rare neurodegenerative disorder of the central nervous system characterized by unwanted choreatic movements, behavioral and psychiatric disturbances and dementia. "Crmp1 is also found within mutant Huntingtin inclusions, and suppresses neurotoxicity in Huntington’s disease models." (PMID 34933920, 2022).
lung adenocarcinoma (2 papers, 2011 to 2014). A carcinoma that arises from the lung and is characterized by the presence of malignant glandular epithelial cells. "In human lung adenocarcinoma, CCN2 inhibits metastasis and invasion by a CRMP-1-dependent mechanism." (PMID 24637722, 2014).
prostate carcinoma (2 papers, 2014 to 2023). A carcinoma that arises from epithelial cells of the prostate gland. "The authors also analyzed the expression patterns of all five members of the CRMP gene family (CRMP1-5) in benign prostate hyperplasia and prostate cancer tissues." (PMID 24765134, 2014). "CRMP1 inhibits prostate cancer cell migration and metastasis by suppressing EMT." (PMID 36820942, 2023).
autoimmune encephalitis (1 paper, 2025). Inflammation of the brain secondary to an immune response triggered by the body itself. "The other three patients with coexisting anti‐CRMP1 and anti‐CRMP2 Abs were diagnosed with autoimmune encephalitis (anti‐GFAP antibody), possible Wernicke encephalopathy, and subacute combined degeneration, respectively." (PMID 40583162, 2025).
Autoimmunity (1 paper, 2022). The occurrence of an immune reaction against the organism's own cells or tissues. "Alternatively, cell-permeable peptides that compete with CRMP1/2-Ser522 may be effective if used with appropriate cell-targeting vehicles to avoid the development of autoimmunity." (PMID 35523582, 2022).
colon cancer (1 paper, 2013). "Among the group of the most consistently hypermethylated genes in both human colon cancer and mouse intestinal adenoma (48 genes), we found Cdh4, Crabp1, Crmp1, Dbc1, Duox1, Grm7, Hand1, Hs3st2, Pcdh17 and Pdpn, which have previously been suggested as cancer biomarkers." (PMID 23408899, 2013).
congenital heart disease (1 paper, 2020). A heart disease that is present at birth. "For example, CRMP1 has been demonstrated as a potential candidate for left-sided congenital heart disease." (PMID 32423033, 2020).
cortical dysplasia (1 paper, 2017). "And FSCN1, CRMP1, NDRG1, DPYSL5, MAP4, and FABP3 were selected for validation and identified to be increased in childhood cortical dysplasia patients, while PRDX6 and PSAP were identified decreased." (PMID 28222113, 2017).
encephalitis (1 paper, 2025). An acute inflammatory process affecting the brain parenchyma. "Among the 14 patients diagnosed with encephalitis/encephalomyelitis, 10 had CRMP1 Abs, 2 had anti‐CRMP3, 1 had anti‐CRMP5, and 1 had co‐existence of anti‐CRMP1 and anti‐CRMP2 Abs." (PMID 40583162, 2025).
Myelopathy (1 paper, 2025). Myelopathy is an descriptive term, referring to pathology leading to a neurologic deficit related to the spinal cord. "Among the 8 patients with non‐inflammatory encephalopathy/myelopathy, 3 had anti‐CRMP1 Abs, 1 had anti‐CRMP2, 1 had anti‐CRMP4, 2 had co‐existence of anti‐CRMP1 and CRMP2 Abs, and 1 had co‐existence of anti‐CRMP1 and anti‐CRMP3 Abs." (PMID 40583162, 2025).
ovarian carcinoma (1 paper, 2018). A malignant neoplasm originating from the surface ovarian epithelium. "It is interesting that both CRMP1 and CRMP4 were expressed at mRNA level in several ovarian cancer cell lines." (PMID 29396402, 2018). "It is important to note that CRMP1 and CRMP4 also are expressed in ovarian cancer cells." (PMID 29396402, 2018). "Thus, it is possible that FER might also phosphorylate CRMP1 or CRMP4 at Y479 and Y499 in ovarian cancer cells since these two sites are highly conserved." (PMID 29396402, 2018).
pancreatic cancer (1 paper, 2014). "Of all the CRMP family members (CRMP1-5), only CRMP4 expression was found to significantly increase in pancreatic cancer compared with the corresponding non-cancerous pancreas tissues." (PMID 24765134, 2014).
pituitary tumor (1 paper, 2015). A benign or malignant neoplasm affecting the pituitary gland. "Dysregulation of CRMP1 has been reported in brain, lung, and prolactin pituitary tumors." (PMID 26009886, 2015).
temporal lobe epilepsy (1 paper, 2017). A localization-related (focal) form of epilepsy characterized by recurrent seizures that arise from foci within the temporal lobe, most commonly from its mesial aspect. "Interestingly, in temporal lobe epilepsy (TLE) patients and animal models, decreased CRMP1 expression was reported." (PMID 28222113, 2017).
tumor (14 papers, 2011 to 2025). "In prolactin-secreting pituitary adenoma, CRMP1 was associated with tumor progression." (PMID 26009886, 2015). "In addition, CRMP1 has also been implicated in tumor invasion suppression." (PMID 39669252, 2023). "Moreover, transcript abundance of CRMP1 was negatively associated with tumor invasiveness." (PMID 26009886, 2015). "Seven genes were associated with recurrence and progression: ADAMTS6, CRMP1, PTTG, ASK, CCNB1, AURKB, and CENPE, while ADAMTS6, CRMP1, ASK, CCNB1, and CENPE were also associated with tumor recurrence and progression." (PMID 41303810, 2025). "Collapsin Response Mediator Protein-1 (CRMP1) acts as a tumor suppressor and exhibits reduced expression in advanced PCa tissues." (PMID 39055653, 2024). "CRMP1 acts to suppress tumor proliferation, migration, invasion and formation of filopodia and intense stress fibers in MB." (PMID 26009886, 2015). "Functional studies demonstrated that depletion of CRMP1 enhanced tumor invasion, whereas increased expression had an opposite effect in glioblastoma." (PMID 26009886, 2015). "NF-kappaB promotes tumor invasion by down-regulating expression of collapsin response mediator protein-1 (CRMP-1), an invasion suppressor gene." (PMID 24213137, 2011). "Cumulative evidence indicates that CRMP1 also contributes to tumor pathogenesis." (PMID 26009886, 2015). "Recent studies provide evidence that CRMP1 participates in tumor progression." (PMID 26009886, 2015). "A study comparing CRMP1 and LCRMP1 expression levels in tumor specimens obtained from 142 patients with NSCLC indicated that patients with low levels of CRMP1 expression or high levels of LCRMP1 expression had a poorer overall and disease-free survival." (PMID 24765134, 2014). "NEC-like IDH2 and NEC-like SMARCA4/ARID1A tumors also demonstrated strong overexpression of proteins specific for neurons or cells of the diffuse neuroendocrine system such as UCHL1, CRMP1 and ENO2, strongly indicating a neuroendocrine differentiation for both tumor classes." (PMID 36443295, 2022). "Overall, we speculated then that CRMP1 is negatively regulated by HMGA1 and it is functionally important in MB tumor biology." (PMID 26009886, 2015).
cancer (12 papers, 2012 to 2023). A tumor composed of atypical neoplastic, often pleomorphic cells that invade other tissues. "LCRMP-1, a novel isoform of CRMP-1, can promote cancer cell migration, invasion and associate with poor clinical outcome in patients with non-small-cell lung cancer (NSCLC)." (PMID 22363707, 2012). "This is well in line with the reported role of CRMP1 in neuronal differentiation and its previous use as a marker gene in neuroblatoma gene expression panels as well as its usefulness as a prognostic and diagnostic marker in other cancers." (PMID 34202325, 2021). "LCRMP-1 can promote filopodia formation, cancer cell migration, invasion through functionally against CRMP-1, and its expression correlates with poor clinical outcome in non-small-cell lung cancer (NSCLC) patients." (PMID 22363707, 2012). "LCRMP1 and CRMP1 exhibit opposing functions in the regulation of cancer cell invasion and metastasis, which may implicate this pathway as a potential anticancer target." (PMID 24765134, 2014). "Since LCRMP-1 and CRMP-1 have opposite function on cancer migration and invasion, whether the function of LCRMP-1 may be regulated by GSK3β should be further studied." (PMID 22363707, 2012). "For instance, downregulation of tumor suppressor genes, such as CRMP-1, NM23, and CTGF were shown to promote metastasis in several cancers." (PMID 29673312, 2018). "Collapsin response mediator protein-1 (CRMP-1) suppresses neuronal growth cone extension during development, and is also known as a cancer invasion suppressor." (PMID 22363707, 2012).
mental illness (5 papers, 2021 to 2026). "These include five genes encoding proteins that aggregate in neurodegenerative and/or mental illness: CRMP1 (also called DPYSL1), DISC1, MAPT (encoding the Tau protein), PRKN (also called PARK2, encoding Parkin), and SOD1." (PMID 42194081, 2026). "In this study, we showed that the identified CRMP1 variants affect neurite outgrowth, which is a characteristic phenotype associated with many neurodevelopmental/psychiatric disorders." (PMID 36511780, 2022). "While altered CRMP1 levels have been reported in psychiatric diseases, genetic variants in CRMP1 gene have never been linked to human disease." (PMID 36511780, 2022). "The second part of the review addresses the known proteins whose aggregation in brain tissue has been observed in psychiatric disorders (amyloid, tau protein, α-synuclein, DISC-1, disbindin-1, CRMP1, SNAP25, TRIOBP, NPAS3, GluA1, FABP, and ankyrin-G)." (PMID 36430976, 2022).
neurodevelopmental disorder (2 papers, 2022 to 2024). A behavioral and cognitive disorder with onset during the developmental period that involves impaired or aberrant development of intellectual, motor, or social functions. "We searched the PubMed and Web of Science databases, and found the only article on the association between CRMP1 and human neurodevelopmental disorders." (PMID 39758889, 2024). "Disruptions in CRMP1’s function, such as those caused by genetic variants, can lead to neurodevelopmental disorders, highlighting the importance of CRMP1 in brain health and function." (PMID 39758889, 2024). "Through the bioinformatics analysis of three CRMP1 cases and the analysis of the effect of genetic variants on protein structure, it was emphasized that CRMP1 is related to human neurodevelopmental disorders." (PMID 39758889, 2024). "To date, only one report has linked genetic variations in the CRMP1 gene to neurodevelopmental disorders in humans." (PMID 39758889, 2024). "Our report may provide evidence for an association between the CRMP1 gene and neurodevelopmental disorders." (PMID 39758889, 2024). "Our report may provide evidence for an association between the CRMP1 gene and neurodevelopmental disorders (NDDs)." (PMID 39758889, 2024).
neurological diseases (2 papers, 2022). "As a future perspective, it will be interesting to find other CRMP1 variants and elucidate the role of specific residues in various neuronal process and associate with the phenotypic spectrum of neurological diseases." (PMID 36511780, 2022). "Our report adds CRMP1 to list of other CRMP genes linked to neurological disorders and underlines the important role of CRMP1 in the nervous system development and function." (PMID 36511780, 2022).
infection (1 paper, 2021). The state of being infected such as from the introduction of a foreign agent such as serum, vaccine, antigenic substance or organism. "Following infection, endogenous CRMP1 protein levels were reduced by ∼60% as determined by immunoblotting." (PMID 33771901, 2021).
CRMP1 also shares sentences with these, for which no sentence is quoted: Alzheimer disease (2 papers); attention deficit-hyperactivity disorder (2); Intellectual disability (2); medulloblastoma (2); Anxiety (1); asthma (1); cognitive deficits (1); colorectal cancer (1); developmental delay (1); ectodermal dysplasia (1); Ellis-van Creveld syndrome (1); encephalomyelitis (1); endometrial cancer (1); esophageal cancer (1); hepatocellular carcinoma (1); hereditary spastic paraplegia (1); intracerebral hemorrhage (1); mental disorder (1); muscular dystrophy (1); neurodegenerative disease (1); renal cell carcinoma (1); Subacute Combined Degeneration (1); tobacco use disorder (1); Wernicke encephalopathy (1).